KRT77 (keratin 77)
Description:
Structural component of intermediate filaments in epithelial cells of stratified epithelia. Assembles into heteropolymers with a type I keratin, forming keratin intermediate filament networks contributing to epithelial integrity.
Synonyms: KRT1B; K1B
Tractability: Antibody: its Gene Ontology location is reachable by antibodies, with medium confidence; the Human Protein Atlas places it where antibodies can reach. PROTAC: ubiquitination databases record sites on it.
Gene: Protein-coding gene on chromosome 12 (52,689,626 to 52,703,524, reverse strand). Ensembl gene ENSG00000189182.
Subcellular location (Human Protein Atlas): Nuclear membrane; Plasma membrane
Pathways (Reactome):
Developmental Biology: Formation of the cornified envelope; Keratinization
Gene Ontology:
Molecular function: protein binding; structural constituent of skin epidermis
Biological process: intermediate filament organization; keratinization
Cellular component: cytoskeleton; extracellular exosome; cytosol; keratin filament; cornified envelope
Genetic constraint (gnomAD): Loss-of-function variants: 40 observed, 46.92 expected, observed/expected ratio (o/e) 0.85, 90% interval 0.66 to 1.11. The upper end of that interval is the gene's LOEUF score, 1.11, which puts it in group 4 of 6, group 1 being the genes least tolerant of losing a copy. Missense variants: 728 observed, 720.53 expected, observed/expected ratio (o/e) 1.01, 90% interval 0.95 to 1.07. Synonymous variants: 277 observed, 293.18 expected, observed/expected ratio (o/e) 0.94, 90% interval 0.86 to 1.04.
Homologues: Orthologues: chimpanzee KRT77 (98% identical), macaque KRT77 (94% identical), pig KRT77 (79% identical), rabbit KRT77 (79% identical), rat Krt77 (76% identical), mouse Krt77 (74% identical), dog KRT77 (72% identical), guinea pig KRT77 (67% identical). Paralogues in human: KRT1 (60% identical), KRT2 (59% identical), KRT76 (57% identical), KRT3 (57% identical), KRT5 (57% identical), KRT6B (54% identical), KRT6A (54% identical), KRT6C (54% identical), KRT4 (54% identical), KRT75 (53% identical), KRT79 (52% identical), KRT73 (51% identical), and 56 more.
Diseases named in the same sentence as KRT77 in open-access papers:
KRT77 is named in the same sentence as 14 diseases in open-access papers, as found by Europe PMC text mining. Sharing a sentence is not in itself a finding about the gene and the disease. The quoted sentences say what the papers report.
food allergies (1 paper, 2024). "Second, four out of nine signature proteins downregulated in patients with AD and food allergies (i.e., Krt77, Asah1, Ggh, Cat) were significantly decreased in the RoraEKO epidermis vs. the control, indicating RORα could be critical for maintaining the expression levels of these important genes." (PMID 39409027, 2024).
keloid (1 paper, 2022). An irregularly shaped, elevated mark on the skin caused by deposits of excessive amounts of collagen during wound healing. "Most keratins were downregulated in keloids, including KRT10, KRT14, KRT15, KRT19, KRT1, KRT77, and KRT5." (PMID 35435317, 2022).
tumor (1 paper, 2025). "Combinations of different cfRNA transcripts, as well as the KRT77 serum levels, demonstrated a stronger predictive value for tumor subtype compared to individual markers." (PMID 39478658, 2025). "Proteomic analysis of serum samples from PDAC patients with well‐characterized tumor subtypes revealed that several keratins, including KRT2, KRT5, KRT10, and KRT77, were highly abundant in samples from patients with basal‐like tumors." (PMID 39478658, 2025).
KRT77 also shares sentences with these, for which no sentence is quoted: cancer (2 papers); Astigmatism (1); epidermolytic ichthyosis (1); gout (1); hair disorder (1); liver disease (1); lymphoma (1); osteoarthritis (1); skin disorder (1); squamous cell carcinoma (1); thyroid cancer (1).